EPO (erythropoietin)
Diseases named in the same sentence as EPO in open-access papers (continued):
Sharing a sentence is not in itself a finding about the gene and the disease.
malaria (continued). "In this study, semi-immune children between 5–15 years old with asymptomatic malaria, had lower Hb levels, increased reticulocyte numbers and erythropoietin levels as well as TNF-α levels, compared to healthy non-malaria carriers, indicating dyserythropoiesis." (PMID 33253198, 2020). "In particular, we sought to identify cytokines and bio-clinical parameters that correlated with EPO levels during CM but did not correlated with EPO levels in NCM malaria patients." (PMID 27441662, 2016). "In murine models, the outcome of malaria is sensitive to experimental manipulation of multiple host innate response molecules, such as tumor necrosis factor (TNF), interferon-γ, and erythropoietin, suggesting their role in mediating differential infection outcome." (PMID 23696730, 2013). "Additionally, though not statistically significant, it is worth noting that EPO concentration was lower among subjects with malaria compared to the controls." (PMID 30894794, 2019). "This could be a possible reason for the reduced level of EPO among children with malaria compared to those without malaria." (PMID 30894794, 2019). "In addition, the significant multivariate correlation of EPO, hemopexin and total heme with TNF-α, IL-10, IP-10 and MCP-1 suggests the implication of EPO in the complex network of factors of the immune system influenced by heme during severe malaria." (PMID 27441662, 2016). "In malaria, SMA has multifaceted aetiologies ranging from parasitized red blood cells (pRBC’s) rapture, pRBC’s and non-parasitized red blood cells (npRBC’s) phagocytosis, insufficient erythropoiesis, ineffective haematopoiesis and reduced erythropoietin production." (PMID 27618936, 2016). "EPO was correlated with haemoglobin, irrespective of malaria (R = -0.36, P < 0.001)." (PMID 16321150, 2005).
polycythemia vera (43 papers, 2009 to 2026). "The serum EPO level was elevated, and a bone marrow biopsy returned positive for JAK-2 mutation indicating the diagnosis of polycythemia vera despite the high EPO level." (PMID 39421127, 2024). "In this type, polycythemia vera is a neoplastic disorder characterized by an increase in the number of erythroid progenitor cells and increased sensitivity to EPO secondary to a Janus kinase mutation." (PMID 35805729, 2022). "Co-treatment of mTOR inhibitor with JAK2 inhibitor resulted in synergistic activity against the proliferation of JAK2V617F mutated cell lines and significantly reduced erythropoietin-independent colony growth in patients with polycythemia vera." (PMID 23382981, 2013). "More studies in understanding the role of EPO in bone in specific pathological conditions are warranted as patients with diseases associated with high circulating EPO such as thalassemia, sickle cell disease, and polycythemia vera have debilitating bone conditions." (PMID 32038269, 2019). "Subsequent work-up confirmed polycythemia vera based on the presence of a JAK2 V617F mutation and suppressed erythropoietin levels." (PMID 41893451, 2026). "In this study, we demonstrate for the first time across multiple animal models that FHF significantly alleviates MPN progression, including EPO-induced polycythemia vera (PV)-like, JAK2V617F-driven PV, and MPLW515L-driven essential thrombocythemia (ET) models." (PMID 42078583, 2026). "The sensitivity for polycythemia vera detection was highest with the erythropoietin and systemic immune-inflammation index combination, followed by erythropoietin and the neutrophil lymphocyte ratio." (PMID 38793053, 2024). "Polycythemia vera (PV), one of the chronic myeloproliferative neoplasms, is a clonal hematopoietic stem cell disorder driven by EPO hypersensitive signaling via the JAK2-STAT5 pathway, resulting in excess proliferation of erythroid precursors." (PMID 37578340, 2023). "The EPO levels were reported to be within normal limits or decreased in horses with primary erythrocytosis due to polycythemia vera, which can be confirmed by bone marrow aspiration." (PMID 36495211, 2023). "The most common acquired primary erythrocytosis is polycythemia vera and in these cases the subject’s erythropoietin (EPO) level will be below the normal range because the defect is intrinsic to the stem cells." (PMID 34440325, 2021). "Polycythemia vera is a myeloproliferative neoplasm characterized by erythrocytosis driven by constitutive activation of the erythropoietin (Epo) receptor by mutant JAK2 protein kinase." (PMID 33364111, 2020). "NT157 inhibited erythropoietin-independent colony formation in cells from polycythemia vera patients (p < 0.05)." (PMID 32296029, 2020). "For example, one of the minor criteria of polycythemia vera (PV) according to WHO 2008 classification is the subnormal serum EPO level." (PMID 26525644, 2015). "In contrast to the TEMPI syndrome where the erythrocytosis is driven by highly elevated serum erythropoietin, our patient was found to have polycythemia vera." (PMID 25143825, 2014). "In agreement with this HLA-G antitumor activity in B cell malignancies, we previously showed that soluble HLA-G inhibits the growth of erythropoietin (EPO)-independent colonies in patients suffering from polycythaemia vera." (PMID 24800261, 2014). "Patients with polycythemia vera can present with a high or low serum EPO level." (PMID 39421127, 2024). "Because his EPO level was elevated (70.5 mIU/mL), polycythemia vera was unlikely." (PMID 36890599, 2023). "who demonstrated a substantially reduced cortical thickness in a mouse model of polycythemia vera, and by others who showed that increased levels of erythropoietin (EPO) – the primary hormone responsible for red blood cell production – are associated with loss of bone." (PMID 35222286, 2022).
polycythemia vera (continued). "Interestingly, we also found one patient with polycythemia vera (PV) and one with Myelofibrosis (MF), with low EPO levels with GA genotype, and 3 PV patients with normal EPO levels with AA genotype." (PMID 34899081, 2021). "Primary absolute erythrocytosis, or polycythaemia vera, is an idiopathic myeloproliferative disorder characterised by overproduction of all cell lines in the bone marrow and accompanied by normal to low concentrations of erythropoietin (EPO)." (PMID 31038324, 2019). "Polycythemia vera was finally diagnosed by positive mutation of Janus kinase 2 and negative erythropoietin protein expression." (PMID 19946506, 2009). "Among CMPNs, polycythemia vera (PV) and essential thrombocythemia (ET) present distinctive alterations in iron metabolism and erythropoietin (EPO) levels, reflecting the pathophysiological characteristics of each disease and their impact on erythropoiesis." (PMID 41577837, 2026). "The EPO seems a good marker, however, not a tumour‐specific marker, which can be used in cases of erythrocytosis after the exclusion of other possible causes (doping, excitement, hypoxia, polycythaemia vera and kidney diseases)." (PMID 36495211, 2023). "Polycythemia vera (PV) is a myeloproliferative neoplasm triggered by mutations in the JAK2 gene, which leads to a high production of erythroid cells, irrespective of erythropoietin (EPO)." (PMID 40507944, 2025). "In polycythemia vera, a primary myeloproliferative disorder, splenomegaly is driven by clonal expansion of hematopoietic stem cells, often independent of EPO levels." (PMID 40191193, 2025). "In the myeloproliferative neoplasm (MPN) polycythemia vera (PV), it has been shown that HLA-G inhibits the formation of PV patient derived erythropoietin-independent erythroid colonies and decreased the proliferation of UT7/EPO and HEL cell lines." (PMID 39696628, 2024). "Red cell overproduction is seen in polycythemia vera (PV), a bone marrow myeloproliferative neoplasm characterized by trilinear cell proliferation (WBC, platelets), as well as in secondary erythrocytosis (SE), a group of heterogeneous disorders characterized by elevated EPO gene transcription." (PMID 35304527, 2022). "Workup revealed an atrial septal defect with bidirectional shunting and normal erythropoietin, consistent with secondary erythrocytosis from suspected POS rather than polycythemia vera." (PMID 42317946, 2026). "Polycythemia vera was ruled out in this patient by negative JAK2 testing and normal erythropoietin levels." (PMID 40656289, 2025). "Among these, one of the HighE males had very high Hb (188 g/l), B-Eryt (6.27 × 10^12/l), and hematocrit (56%), necessitating further studies for erythropoietin and the JAK2 gene to rule out polycythemia vera." (PMID 40191210, 2025).
brain injury (40 papers, 2011 to 2025). Acute and chronic (see also brain INJURIES, CHRONIC) injuries to the brain, including the cerebral hemispheres, CEREBELLUM, and brain STEM. "For instance, erythropoietin’s neuroprotective properties have been explored in various preclinical and clinical settings, highlighting its capacity to support neuronal survival and reduce the impacts of brain injuries caused by conditions like hypoxia." (PMID 38804373, 2024). "Recombinant human erythropoietin (EPO), a cytokine known as its role in erythropoiesis, is a promising neuroprotective treatment in brain injury." (PMID 36699298, 2022). "Our data show that EPO can modulate hippocampal network maturation and support ongoing trials of the use of EPO in clinical neonatology to stimulate neuronal maturation after perinatal brain injury (PBI)." (PMID 33495244, 2021). "Other interventions including folic acid and erythropoietin are protective against behavioral and neuroanatomical changes after traumatic brain injury in piglet and rat models." (PMID 31243296, 2019). "Previously, we and others have shown that EPO treatment following perinatal brain injury promotes the genesis, survival, and differentiation of neural cells in the developing and mature CNS, and reduces calpain-mediated injury." (PMID 29971038, 2018). "The neuro-restorative effects of EPO have been ascribed to direct effects on neural stem cells, in rodent models of ischemic and traumatic brain injury." (PMID 30597853, 2018). "In traumatic brain injury model, EPO with a range of 1000 to 7000 IU/kg was used and the medium dose of EPO (5000 IU/kg) showed a significant improvement in histological and functional outcomes compared with the lower or higher EPO dose groups." (PMID 29385149, 2018). "The mechanism for the Epobis-improved memory of healthy animals is unclear, since most studies of the effects of EPO and EPO derivatives on memory have been performed on animals exposed to a brain injury or undergoing a disease model." (PMID 27990061, 2016). "Laboratory and clinical studies demonstrate a possible beneficial effect of erythropoietin in improving outcomes in the traumatic brain injury cohort." (PMID 25884605, 2015). "In adults, EPO level in cerebrospinal fluid was observed to be 30-fold lower than serum levels in patients with traumatic brain injury." (PMID 24918289, 2014). "From a functional point of view, long-term EPO treatment after P3 HI brain injury promoted whisker stimulated somatosensory functional recovery at P27–P28 to near normal levels." (PMID 24755676, 2014). "This study aims to include 606 patients having traumatic brain injury to evaluate EPO for brain protection but renal biomarkers will be also analyzed." (PMID 23033926, 2012). "Preclinical and early clinical studies suggest that combining EPO with TH and neuroprotectants such as melatonin may enhance outcomes following perinatal brain injury." (PMID 41012526, 2025). "Converging evidence suggests that erythropoietin (Epo) may be effective in alleviating symptoms of many neurological conditions, including traumatic brain injury and neurodegenerative disorders." (PMID 40321747, 2025). "Additionally, the primary objectives of the study were to evaluate the effects of erythropoietin and a high transfusion threshold in acute brain injury, under the assumption that there would be minimal interaction between these two interventions." (PMID 40329392, 2025). "Erythropoietin (EPO), supports the function and survival of neurons through astrocytes and has a protective role in neonatal asphyxia brain injury; yet, its mechanism of action remains unclear." (PMID 35167649, 2022). "In addition to its established function in erythropoiesis, erythropoietin (EPO) is considered a potential therapeutic strategy for various types of brain injuries." (PMID 33126773, 2020). "Last but not least, our study is focused on the immunomodulatory effects of EPO on brain trauma." (PMID 29201540, 2017).
brain injury (continued). "It aims to determine whether the administration of erythropoietin compared to placebo improves neurological outcome in patients with moderate or severe traumatic brain injury at six months after injury." (PMID 25884605, 2015). "In rodent models of ischemic brain injury and traumatic brain injury, EPO treatment was suggested to reduce neuronal death and associated astrocyte activation, leukocyte and microglia recruitment to the site of infarction or injury, and proinflammatory cytokine production." (PMID 24918289, 2014). "However, a multicenter study showed that TH combined with erythropoietin increased the risk of thrombosis and did not reduce the incidence of local brain injury, but subacute brain injury was more common." (PMID 40401026, 2025). "Thus far, erythropoietin has shown promise as a neuroprotective agent and future implementation may greatly improve outcomes for NE infants with brain injury in LMICs." (PMID 34175900, 2021). "Our study found that EPO decreased brain edema at 1 and 3 days postinjury, which is consistent with Okutan, Turkoglu, Gok, & Beskonakli (2008) study showing the EPO treatment in cold brain injury decreased brain edema via antiapoptotic and anti‐inflammatory actions." (PMID 29201540, 2017). "In neonatal hypoxic-ischemic brain injury, a variety of potential early therapeutics have broadly been categorized into anti-oxidative, anti-inflammatory, anti-apoptotic, and anti-excitotoxic mechanisms, with melatonin and erythropoietin covering multiple mechanisms." (PMID 26846184, 2016). "Preterms with brain injury proved to have significant increase of S100B and NSE, followed by increase of EPO and enhanced mobilization mainly of HSCs, eEPCs and lEPCs." (PMID 37292373, 2023). "However, some studies have reported beneficial effects of hypothermia, erythropoietin, stem cell therapy, anti-cytokine therapy and metformin in ameliorating several different facets of damage to the NVU after HI-related brain injury in the perinatal period." (PMID 32060970, 2020). "Indeed, it is through EPO's signaling action on structural and functional connectivity, neural networks, and excitatory/inhibitory balance of fundamental circuitry that EPO therapy may improve motor and cognitive function following early brain injury, including TBI." (PMID 29971038, 2018). "In brain, the protective effects of EPO are mediated via STAT3 activation, which promotes increased Bcl-2 and Bcl-xL in animal models of experimental intracerebral hemorrhage, and traumatic brain injury, and facilitates neuritogenesis." (PMID 24918289, 2014). "Given the ligand-receptor mismatch found in preterm infants, and the supplementation of endogenous MLT signaling, the combination of EPO and MLT could be a reasonable and indispensable therapeutic strategy for infants with brain injury, as could therapies that support HIF2α." (PMID 37546540, 2023). "Similarly, if EPO and IGF-1 levels in serum are not changed after brain injury, it would be rather impossible that systematically administration of them to be of value." (PMID 37292373, 2023).
COVID-19 (39 papers, 2020 to 2025). A disease caused by infection with severe acute respiratory syndrome coronavirus 2. "On one hand, some studies have indeed shown that lower serum EPO levels were associated with more severe COVID-19 and poor prognosis; on the other hand, other ones show a very limited efficacy of the treatment." (PMID 40126283, 2025). "Under conditions of hypoxia, such as those found in severe pneumonia caused by bacterial infection or related to COVID-19, the kidneys react by increasing the production of erythropoietin." (PMID 37834401, 2023). "Lastly, the use of erythropoietin (EPO) in the setting of COVID-19 has been controversial, and one should balance the risk of increasing thrombosis risk against the immunomodulatory effects of EPO." (PMID 35371886, 2022). "Many of the pro-inflammatory cytokines upregulated in COVID-19, such as tumor necrosis factor-α and interleukin-1, can cause lowering of erythropoietin production." (PMID 36297178, 2022). "Recent counterintuitive findings of decreased serum erythropoietin levels in severe COVID-19 not only support a relative deficiency of erythropoietin in this condition, which can be therapeutically addressed, but also made us coin the term ‘hypoxia paradox’." (PMID 34565332, 2021). "Hypoxemia associated with COVID-19 is one of them, which induces erythropoietin (EPO) release, as reported in several similar lung diseases." (PMID 34870233, 2021). "An 80-year-old woman with multiple comorbidities, including myelofibrosis under erythropoietin therapy, presented with severe coronavirus disease 2019 (COVID-19) pneumonia." (PMID 41141097, 2025). "Regarding predictive parameters of critical COVID-19 occurrence, in multivariable logistic regression analysis, a combination of EPO and ferritin/hepcidin showed very good diagnostic performances and correctly classified 88% of cases, with an AUC of 0.838 (0.749–0.906)." (PMID 38892911, 2024). "EPO and ferritin/hepcidin might help to identify on-admission COVID-19 patients at risk of developing a critical form of the disease." (PMID 38892911, 2024). "Implementation of EPO and ferritin/hepcidin in clinical practice might help to identify on-admission COVID-19 patients who are at risk of developing critical forms of disease." (PMID 38892911, 2024). "Substitution of erythropoietin might overcome this ‘hypoxia paradox’ caused by deranged signaling and improve survival/functional status of COVID-19 patients and their long-term outcome." (PMID 34565332, 2021). "EPO is probably in many instances of COVID-19 associated cytokine storm a better option than the ultima ratio immunosuppression, which may weaken, complicate or even endanger proper host defense." (PMID 32546125, 2020). "In the endothelium, NOS3 has a secretory effect on erythropoietin, which protects children and young adults from COVID-19." (PMID 40142738, 2025). "Elevated amounts of dsRNA were detected in short 5′-pppA RNAs and full-length mRNAs, including erythropoietin (EPO) mRNA and COVID-19 vaccine mRNA harbouring the complete sequence of the spike protein, where terminal adenosine was employed during IVT reaction." (PMID 39704128, 2025). "Serum levels of iron and hepcidin are low in COVID-19 patients, whereas erythropoietin (EPO) and haptoglobin levels significantly decline in critical and deceased patients." (PMID 38555403, 2024). "In line, recent studies from our research group have shown a direct correlation between decreased serum erythropoietin levels and increased risk of mortality among high-altitude ICU patients with COVID-19." (PMID 39882326, 2024). "Only EPO, IL-6, and hepcidin/EPO differentiated patients with critical COVID-19 from those with severe disease course." (PMID 38892911, 2024). "EPO mRNA levels: We have previously shown upregulation of EPO expression in the nasopharyngeal swab samples of COVID-19 patients with mild symptoms." (PMID 36611805, 2022).